HCP5 (HLA complex P5)
Diseases named in the same sentence as HCP5 in open-access papers (continued):
Sharing a sentence is not in itself a finding about the gene and the disease.
cancer (49 papers, 2018 to 2025). A tumor composed of atypical neoplastic, often pleomorphic cells that invade other tissues. "HCP5 expression was abnormally high in many cancer types and its dysregulation appears closely linked to progression." (PMID 38643145, 2024). "HCP5 is one lncRNA that has been shown to be associated with several diseases, especially in cancer." (PMID 35399723, 2022). "Studies have pointed that lncRNA HCP5 is associated with the progressions and developments of various cancers and diseases." (PMID 34969363, 2022). "In summary, based on current reported literature, there is significantly association between dysregulation of HCP5 and both prognosis and advanced clinicopathological features in most cancers." (PMID 34923990, 2021). "There is a significantly association between dysregulation of HCP5 and both prognosis and clinicopathological features in various cancers." (PMID 34923990, 2021). "There are more studies showing the involvement of HCP5 lncRNA in innate and adaptive immune response, and associating its expression with some autoimmune diseases and cancer." (PMID 32375397, 2020). "Moreover, it is showed that the AKT signaling, which closely associating with cancer radiotherapy, is affected by HCP5." (PMID 34969363, 2022). "As a cancer-associated lncRNA, HCP5 has been reported in numerous studies." (PMID 35399723, 2022). "To date, there are rare studies linked the HCP5 with cancer therapy." (PMID 34969363, 2022). "In particular, an increased expression of HCP5 – HERV16-derived long non-coding RNA of oncogenic potential in various cancer types could be considered as a cancer diagnostic marker." (PMID 32375397, 2020). "For instance, lncRNA HLA complex P5 (HCP5) is recognized as a carcinogenic driving factor in various cancers." (PMID 39717716, 2025). "It has been well documented that HCP5 functions as oncogenes in various types of cancer, involving HCC, GEM and clear cell RCC." (PMID 38643145, 2024). "Previous researchers have reported that HCP5 can act as a molecular sponge to miRNA in different cancers." (PMID 39201624, 2024). "In line with the present findings, this evidence supports a deleterious influence of HCP5 overexpression on OS in various types of cancer." (PMID 37388937, 2023). "The other cancer treatments, such as chemotherapy and immunotherapy, should be also affected by HCP5 repressed." (PMID 34969363, 2022). "In our study, the results of databases and RT-qPCR have shown that HCP5 was upregulated in cancer tissues and correlated with poor prognosis, which indicates that HCP5 is related to cervical carcinogenesis." (PMID 35399723, 2022). "This is the first meta-analysis to systematically collect studies and to evaluate the potential functions of HCP5 as therapeutic target and prognostic biomarker for human cancers." (PMID 34923990, 2021). "Some cell factors, such as AGAP2-AS1, HCP5, serve as potential targets to inhibit the progression of cancer and improve the chemotherapy efficacy in cancer." (PMID 34603046, 2021). "HCP5, a promising novel cancer-related lncRNA, numerous studies have revealed that HCP5 was dysregulated in various cancers, and that HCP5 has the potential to become a diagnostic biomarker and therapeutic target." (PMID 34923990, 2021). "Human histocompatibility leukocyte antigen (HLA) complex P5 (HCP5) belongs to lncRNAs, and numerous reports have studied the functional roles of lncRNA HCP5 in cancers." (PMID 33439936, 2021). "To further verify our results, we used GEPIA 2 to evaluate the expression level and survival analysis of HCP5 in various cancers." (PMID 34923990, 2021). "The HCP5 high expression group had shorter OS and DFS than the HCP5 low expression group, confirming that up-regulated HCP5 is correlated with poor OS in most human cancers." (PMID 34923990, 2021). "In OSCC cells, overexpression of the long noncoding RNA HCP5 promoted cancer cell proliferation and EMT by adsorbing miR-140-5p." (PMID 34884487, 2021).
cancer (continued). "HCP5 was significantly up-regulated in four cancers and down-regulated in SKCM, which was validated by the GEPIA2 cohort." (PMID 34923990, 2021). "In this regard, association studies, expression data analysis, and knockdown experiments have shown that HCP5 can promote or suppress cancers depending on the HCP5 allelic form and the cancer type." (PMID 31137555, 2019). "The five prognostic genes have all been reported to be associated with human cancer, and three (GAS5, HCP5, and SNHG11) have reported associations with OC." (PMID 31182053, 2019). "In recent years, an increasing number of lncRNA, including HCP5, were found to have potential functions in cancer." (PMID 31137555, 2019). "Interrogation of the TCNG Cancer Network Galaxy Database produced 206 networks for genes regulating or regulated by the HCP5 gene as estimated from publicly available cancer gene expression data." (PMID 31137555, 2019). "Since 2016, at least ten different cancer types were found to occur and/or progress by way of the HCP5–miRNA–gene regulator interactions or the ceRNA mechanism." (PMID 31137555, 2019). "The involvement of HCP5 lncRNA in various human diseases and cancers underscores the importance of understanding its functions in the ceRNA networks as an important step towards future drug development." (PMID 31137555, 2019). "A more detailed account of HCP5 RNA interaction in micro RNA regulatory networks in cancer is provided in the following section." (PMID 31137555, 2019). "The lncRNA HCP5 (HCP5) was recently identified as an oncogene in several malignant tumors." (PMID 38071681, 2024). "P65 expression was positively correlated with HCP5 expression in cancer tissues." (PMID 39201624, 2024). "lncRNA HCP5 has been reported to play crucial roles in various types of cancer." (PMID 39201624, 2024). "In addition, several research studies have revealed abnormal HCP5 expression that correlates with the prognosis of many cancers, making it a potential prognostic biomarker." (PMID 37388937, 2023). "HCP5 promotes cancer development by sponging miR-140-5p, miR−138−5p, miR-29b-3p, and miR-143-3p." (PMID 36248798, 2022). "The result shows that HCP5 arises in all three cancer cells compared to the Het-1A cell." (PMID 34969363, 2022). "However, there are few studies that reported that HCP5 is connected with the radiosensitivity of cancer." (PMID 34969363, 2022). "Furthermore, we used the 31 pairs of adjacent cancer and cancer tissues to test the expression levels of HCP5 using RT-qPCR." (PMID 35399723, 2022). "Besides, dysregulation of HCP5 is also related to cell proliferation, apoptosis, and drug resistance in many other cancers 47-49." (PMID 35399723, 2022). "Several studies have explored the relationship between HCP5 and metastasis and prognosis in cancer." (PMID 35693013, 2022). "LncRNA HLA complex P5 (HCP5) was a well-acknowledged oncogenic driver in various cancers." (PMID 34187448, 2021). "Eight of them reported that HCP5 was up-regulated in cancer tissues and function as the oncogenes." (PMID 34923990, 2021). "However, the molecular mechanisms by which HCP5 functions in cancer are complex and diverse, thus our research focused on the possible mechanisms of HCP5 in OS." (PMID 33439936, 2021). "The results revealed that HCP5 was significantly up-regulated in four cancers (CHOL, ESCA, LAML and PAAD), and that strongly associated with poor prognosis; HCP5 was down-regulated in SKCM, and that HCP5 high expression group had longer OS than the HCP5 low expression group." (PMID 34923990, 2021). "The role of the long non-coding RNA (lncRNA) HCP5 in cancer remains controversial." (PMID 33868993, 2021). "Interestingly, the result in this paper was consistent with previous studies, suggesting that HCP5 universally had an oncogenic role in cancers." (PMID 33439936, 2021).
cancer (continued). "Therefore, we systematically selected relevant literatures and performed this meta-analysis to conduct an evidence-based evaluation of the prognostic role of lncRNA HCP5 in various cancers." (PMID 34923990, 2021). "Furthermore, we used two public databases (GEPIA 2 and NGDC) to validate HCP5 expression level in various cancers." (PMID 34923990, 2021). "Moreover, the relationship between HCP5 expression levels and clinical attributes has been analyzed according to the specific cancer types." (PMID 34923990, 2021). "HCP5 may be functions as a novel potential prognostic biomarker and therapeutic target in multiple human cancers." (PMID 34923990, 2021). "HCP5 expression in various types of cancer was also verified in NGDC." (PMID 34923990, 2021). "NGDC was used to further validate the expression of HCP5 in various cancers." (PMID 34923990, 2021). "Moreover, the abnormal expression of HCP5 is closely related to cell proliferation, migration, invasion, apoptosis, lymphatic metastasis, and drug resistance in various cancers." (PMID 34222007, 2021). "Firstly, to explore whether HCP5 is dysregulated in GC progress, HCP5 expression was detected in 62 paired GC tissues and corresponding para-carcinoma normal tissues by qRT-PCR." (PMID 33613117, 2021). "HCP5 has been found upregulated or downregulated in a number of different cancers." (PMID 31137555, 2019). "Judging from the recent new findings about the possible oncogenic role of HCP5 as a ‘sponge’ for sequestering regulatory miRNA in cancer, new insights about its diverse mechanisms and functions in health and disease undoubtedly will continue to emerge and surprise in the near future." (PMID 31137555, 2019). "Since ferroptosis is a new type of programmed cell death defined in recent years, and some research has suggested that ferroptosis may be involved in cancer development, we aimed to investigate whether HCP5-132aa regulates ferroptosis to promote the malignant phenotype of TNBC." (PMID 36980766, 2023). "Moreover, HCP5 is able to target multiple factors in several cancers and other diseases." (PMID 35602292, 2022). "Further functional prediction revealed that HCP5 may participate in some cancer-related pathways." (PMID 34923990, 2021). "Similarly, the interaction of HCP5, microRNA, and protein coding genes in cancer suggests that HCP5 could be targeted for knockdown or knockout in antitumor therapeutics." (PMID 31137555, 2019). "From the mechanistic point of view, HCP5 either acts as a differentially methylated site involved in epigenetic regulation, or it is involved in transcriptional regulation of protein coding genes by sequestering miRNA as reported for a variety of different cancers." (PMID 31137555, 2019). "Overexpression of HCP5 stabilizes ferroptosis-related genes via the HCP5-132aa/YBX1/ELAVL1 ternary complex, suppressing ferroptosis and accelerating cancer progression." (PMID 41304936, 2025). "The levels of HCP5-132aa were found to be increased in TNBC cell lines and primary cancer tissues, compared to their corresponding parental cell lines and precancerous tissues, respectively." (PMID 36980766, 2023). "Consistent with previous reports of other cancers, HCP5 expression was also upregulated in LSCC cells, and HCP5 was an oncogene." (PMID 36248798, 2022). "Various expression studies have shown that HCP5 is a useful biomarker for interferon and IL28-related inflammatory response, monocyte response to influenza A infection, and various cancers." (PMID 31137555, 2019). "Regarding to HCP5 and LINC00511, a variety of studies have also suggested that they act as two crucial oncogenes in human cancers." (PMID 31061236, 2019). "Additionally, HCP5 expression is confirmed to be prominently increased in oral SCC, which has a key role in promoting cancer cell invasion." (PMID 36248798, 2022). "We also verified lncRNA HCP5 expression in 624 ESCC tissues and 1691 non cancer control tissues." (PMID 34488675, 2021).
cancer (continued). "We first filtrated ER lncRNAs with continuous status in multiple cancers (EA samples/ES samples > 2 or <0.5 in at least three cancer types) and obtained six EA lncRNAs (PVT1, PSMD5-AS1, FAM83H-AS1, MIR4458HG, HCP5, and GAS5) and three ES lncRNAs (CTD-2201E18.3, HCG11, and AC016747.3)." (PMID 34222227, 2021). "The results in OCs were consistent with other cancer studies, and new findings were made; for example, five lncRNAs (MIR31HG34, HOTAIRM1, MIR155HG, ITGB2-AS1, HCP5, and SH3PXD2A-AS134) were reported in other different cancers, which confirmed the reliability of our newfound biomarkers." (PMID 31462944, 2019). "Numerous studies introduced that HCP5 overexpression promoted cancer cell malignant behaviors, such as epithelial-mesenchymal transition (EMT), proliferation, migration, invasion and angiogenic ability, suggesting the vital role of HCP5 in cancer initiation and progression." (PMID 34187448, 2021).
adenocarcinoma (1 paper, 2019). A common cancer characterized by the presence of malignant glandular cells. "Recently, TGFbeta was shown to induce over-expression of the HCP5 gene and activity of the S-mothers against decapentaplegic homolog 3 (SMAD3) protein complex in adenocarcinomas." (PMID 31137555, 2019).
HCP5 also shares sentences with these, for which no sentence is quoted: infection (3 papers); Kawasaki disease (3); renal cell carcinoma (3); graft versus host disease (2); oral squamous cell carcinoma (2); pancreatic adenocarcinoma (2); rheumatoid arthritis (2); Sjögren syndrome (2); Stevens-Johnson syndrome (2); acute lymphoblastic leukemia (1); ankylosing spondylitis (1); asthma (1); autism (1); benign tumor (1); brain cancer (1); brain tumors (1); chickenpox (1); cholangiocarcinoma (1); clear cell renal cell carcinoma (1); cutaneous squamous cell carcinoma (1); digestive system carcinoma (1); gastric tumor (1); Graves disease (1); hyperthyroidism (1); Insulin resistance (1); invasive ductal carcinoma (1); liver cancer (1); malignant glioma (1); mononucleosis (1); multiple sclerosis (1).
A further 9 diseases each share a sentence with HCP5 in 1 paper.